ADCY9 (adenylate cyclase 9)
Description:
Adenylyl cyclase that catalyzes the formation of the signaling molecule cAMP in response to activation of G protein-coupled receptors. Contributes to signaling cascades activated by CRH (corticotropin-releasing factor), corticosteroids and beta-adrenergic receptors.
Synonyms: ACIX; AC9
Tractability: Antibody: UniProt places it where antibodies can reach, with high confidence; its Gene Ontology location is reachable by antibodies, with high confidence; UniProt predicts a signal peptide or a membrane-spanning region; the Human Protein Atlas places it where antibodies can reach. PROTAC: ubiquitination databases record sites on it; a small molecule that binds it is known.
Target class: Enzyme; Lyase
Safety:
Unwanted effects reported when the protein is acted on. In parentheses: how it was acted on, where the effect was seen, and who reports it.
cholesterol efflux response (source: ClinPGx)
major adverse cardiac events (source: ClinPGx)
major adverse cardiac events (MACE) and cholesterol efflux response (source: ClinPGx)
Gene: Protein-coding gene on chromosome 16 (3,953,387 to 4,116,442, reverse strand). Ensembl gene ENSG00000162104.
Subcellular location: Cell membrane
Subcellular location (Human Protein Atlas): Cytosol; Plasma membrane; Basal body; Primary cilium
Pathways (Reactome):
Signal Transduction: Adenylate cyclase activating pathway; G alpha (i) signalling events; G alpha (s) signalling events; G alpha (z) signalling events; GPER1 signaling; Hedgehog 'off' state; PKA activation
Disease: ADORA2B mediated anti-inflammatory cytokines production; FCGR3A-mediated IL10 synthesis
Metabolism: Glucagon signaling in metabolic regulation; PKA activation in glucagon signalling
Cellular responses to stimuli: High laminar flow shear stress activates signaling by PIEZO1 and PECAM1:CDH5:KDR in endothelial cells
Neuronal System: Adenylate cyclase inhibitory pathway
Transport of small molecules: Vasopressin regulates renal water homeostasis via Aquaporins
Gene Ontology:
Molecular function: adenylate cyclase activity; protein binding; phosphorus-oxygen lyase activity
Biological process: adenylate cyclase-activating adrenergic receptor signaling pathway; adenylate cyclase-activating G protein-coupled receptor signaling pathway; cAMP biosynthetic process; cellular response to glucagon stimulus; renal water homeostasis; signal transduction; vascular endothelial cell response to laminar fluid shear stress; cyclic nucleotide biosynthetic process; intracellular signal transduction; system process
Cellular component: membrane; plasma membrane; axon; dendrite
Genetic constraint (gnomAD): Loss-of-function variants: 50 observed, 104.87 expected, observed/expected ratio (o/e) 0.48, 90% interval 0.38 to 0.6. The upper end of that interval is the gene's LOEUF score, 0.6, which puts it in group 2 of 6, group 1 being the genes least tolerant of losing a copy. Missense variants: 1,646 observed, 1,872.8 expected, observed/expected ratio (o/e) 0.88, 90% interval 0.84 to 0.92. Synonymous variants: 895 observed, 795.93 expected, observed/expected ratio (o/e) 1.12, 90% interval 1.06 to 1.19.
Homologues: Orthologues: chimpanzee ADCY9 (99% identical), macaque ADCY9 (99% identical), dog ADCY9 (93% identical), rat Adcy9 (92% identical), mouse Adcy9 (92% identical), guinea pig ADCY9 (92% identical), pig ADCY9 (91% identical), rabbit ADCY9 (84% identical), zebrafish adcy9 (58% identical), Drosophila melanogaster Ac13E (35% identical), Caenorhabditis elegans acy-1 (33% identical). Paralogues in human: ADCY5 (24% identical), ADCY6 (24% identical), ADCY8 (23% identical), ADCY2 (22% identical), ADCY3 (22% identical), ADCY1 (22% identical), ADCY7 (21% identical), ADCY4 (21% identical), GUCY2F (12% identical), GUCY2D (12% identical), NPR1 (12% identical), NPR2 (11% identical), and 5 more.